PTPRG (protein tyrosine phosphatase receptor type G)
Diseases named in the same sentence as PTPRG in open-access papers (continued):
Sharing a sentence is not in itself a finding about the gene and the disease.
cancer (17 papers, 2009 to 2025). A tumor composed of atypical neoplastic, often pleomorphic cells that invade other tissues. "Although PTPRG is recognized as a key regulator in cancer, its role in cancer-associated metabolic reprogramming remains poorly understood." (PMID 41323734, 2025). "This further supports the important function of PTPRG in regulating a hallmark of cancer, namely angiogenesis, in NPC through Akt signaling inhibition." (PMID 25970784, 2015). "This is consistent with the functional assay results showing PTPRG inhibits invasion and angiogenesis of the cancer cells and associates with the regulation of the Akt signaling pathway." (PMID 25970784, 2015). "Down-regulation and promoter hypermethylation are critical factors associated with PTPRG inactivation in cancer and have been observed in sporadic and Lynch syndrome colorectal cancer, ovarian, breast, and lung cancers, gastric cancer, chronic myeloid leukemia, T-cell lymphoma, and NPC." (PMID 25970784, 2015). "Protein tyrosine phosphatase receptor type G (PTPRG) is a member of the tyrosine phosphatase family regulating various biological processes in cancer." (PMID 36405010, 2022). "Overexpression of PTPRG in cancer cells inhibits cell proliferation, while its repression increases proliferation." (PMID 34389752, 2021). "Overexpression of PTPRG in cancer also delays cell cycle re-entry due to increased expression of cell cycle regulators p21cip and p27kip36." (PMID 34389752, 2021). "In contrast, the expression of PTPRC and PTPRG were decreased in cancer tissue compared with normal tissue." (PMID 30126387, 2018). "Protein tyrosine phosphatase receptor type G (PTPRG) is an important tumor suppressor gene in multiple human cancers." (PMID 27602768, 2016). "Furthermore, the correlation of PTPRG phosphatase with inflammatory processes in different normal tissues, including cancer, and the increasing amount of its soluble form (sPTPRG) in plasma, suggest a possible role as inflammatory marker." (PMID 35053232, 2022). "A comprehensive review covering the multiple roles of PTPRG in cancer is currently in press." (PMID 35053232, 2022). "We next investigated whether miR-19b was inversely correlated with PTPRG in cancer tissues." (PMID 27602768, 2016). "However, the mechanism contributing to PTPRG silencing in cancers is largely unknown." (PMID 27602768, 2016). "Among the 21 validated genes, the strikingly decreased transcription of PTPRG and AMN1 and increased transcription of UPP1 potentially support data on cell cycle disturbances relevant to cancer, stem cell and neurodegenerative diseases' research." (PMID 19763259, 2009). "Common CNLs negatively influencing DFS and cancer-specific OS harboured the feline orthologous of multiple HBC-related genes reported as commonly deleted including FOXP1, FBXO25, CSMD1, AGPAT5, PCM1, PTPRG, and PDGFRL15,19,27,28,41–43." (PMID 31969654, 2020).
renal disease (1 paper, 2021). "PTPRG interacts with epidermal growth factor receptor (EGFR), a protein tyrosine kinase containing several phosphorylation sites, and dysregulated EGFR expression has been linked to renal disease." (PMID 34389752, 2021).
PTPRG also shares sentences with these, for which no sentence is quoted: Insulin resistance (3 papers); breast tumor (2); Clear Cell Renal Cell Carcinoma (2); non-alcoholic fatty liver disease (2); ovarian carcinoma (2); acute lymphoblastic leukemia (1); acute myocardial infarction (1); acute vascular disorders of the intestine (1); angina pectoris (1); dementia (1); depression (1); dyslipidemia (1); gastric cancer (1); hematologic cancers (1); hematological malignancies (1); hepatocellular carcinoma (1); Hypertension (1); ischemic stroke (1); kidney tumor (1); liver inflammation (1); lymphoma (1); Lynch syndrome (1); multiple myeloma (1); myeloproliferative diseases (1); Nervous (1); neurodegenerative disease (1); neuroendocrine tumors (1); neurological disorders (1); oral cancer (1); prostate carcinoma (1).
A further 5 diseases each share a sentence with PTPRG in 1 paper.